KLF5 (KLF transcription factor 5)
Diseases named in the same sentence as KLF5 in open-access papers (continued):
Sharing a sentence is not in itself a finding about the gene and the disease.
diabetes (9 papers, 2018 to 2025). "In models of diabetes, cardiac expression levels of Klf5 and Ppara were correlated, suggesting involvement of KLF5 in diabetic cardiomyopathy." (PMID 29942807, 2018). "In conclusion, our results suggest that diabetes increases the level of AGE which enhances the expression of MDM2 via transcription factor KLF5 in colon cells." (PMID 30271790, 2018). "In addition, a recent study showed that patients and mice with diabetes have high Krüppel-like factor-5 (KLF5) mRNA expression." (PMID 35784531, 2022). "Conversely, in type 2 diabetes mellitus model, a hyper-insulin environment, both in vivo and in vitro experiments indicate that KLF5 attenuates VEGF-induced endothelial migration and proliferation and compromises angiogenic function by inhibiting the expression of NOS3." (PMID 33493334, 2021). "Our results revealed new insights into how KLF5 functions play a role in controlling diabetes." (PMID 29670837, 2018). "Inhibiting KLF5 may be a potential pharmacological intervention in controlling diabetes." (PMID 29670837, 2018). "The newly identified KLF5- miR-375 pathway may contribute to diabetes progression." (PMID 29670837, 2018). "We investigated whether KLF5 transcribed the MDM2 animal model of diabetes." (PMID 30271790, 2018). "Cancer tissues had lower levels of KLF5, KLHL13, and CUL3 but higher levels of CEP57L1 than paracarcinoma counterparts, which was exaggerated by the presence of diabetes." (PMID 41443421, 2025). "In conclusion, our results showed that KLF5 directly transcribed MDM2 in vitro in a cell model and in vivo in diabetes mouse colon, which was responsible for AGEs-increased expression of MDM2." (PMID 30271790, 2018). "In a cohort of cancer patients, KLF5, KLHL13, and CUL3 levels were lower, but CA and CEP57L1 were higher in cancer tissues, compared with noncancerous counterparts, which were more obvious in those with diabetes." (PMID 41443421, 2025). "The expression of KLF5, which regulates lipid metabolism, is known to be related to high expression of PPARα in T1DM, whereas FOXO1 is a positive transcriptional regulator of KLF5 in diabetes." (PMID 35784531, 2022).
esophageal cancer (9 papers, 2015 to 2025). A primary or metastatic malignant neoplasm involving the esophagus. "KLF5 promotes proliferation in esophageal keratinocytes and induces cell death in esophageal cancer cells." (PMID 26474386, 2015). "In addition, KLF5 may play an important role in various tumors, including breast cancer, prostate cancer, bladder cancer, skin cancer, colon cancer, and esophageal cancer." (PMID 34367275, 2021). "Moreover, KLF5 induces apoptosis via inducing pro-apoptotic protein Bax in esophageal cancer cells." (PMID 31787746, 2019). "Our data suggest that BAP1 promotes cell proliferation and migration, and enhances the expression of KLF5 and its downstream genes, including CyclinD1 and FGF‐BP1, in the esophageal carcinoma cell line ECA109." (PMID 33529461, 2021). "For other tumor types such as esophageal carcinoma (ESCA), bladder urothelial carcinoma (BLCA) and uterine corpus endometrial carcinoma (UCEC), which had comparable rates of KLF5 amplification and deletion, KLF5 expression changed in accordance to its copy number (bottom 3)." (PMID 33923166, 2021).
liver cancer (9 papers, 2007 to 2023). An epithelial or non-epithelial malignant neoplasm that arises from the liver. "For example, loss of hetero-zygosity for Klf4 and Klf5 has been found in colon, stomach, breast, prostate and liver cancers." (PMID 17925037, 2007). "In liver cancer, miR-145-5p was reported as an inhibitor of cell proliferation by negatively targeting the oncogene Spermatogenesis associated serine-rich 2 (SPATS2) and Kruppel-like factor 5 (KLF5)." (PMID 36214767, 2022). "Here, we identify KLF5 as a key determinant of invasive liver cancer." (PMID 32965165, 2020).
liver cancer (continued). "The miRNA-21 was demonstrated to promote the proliferation, migration, and invasion of liver cancer cells through inhibiting FASLG, SOCS6, and KLF5." (PMID 37704828, 2023). "To investigate the function of KLF5 on EMT in liver cancer cells, we overexpressed or knocked down KLF5 in the liver cancer cell lines HepG2 and Hep3B." (PMID 32965165, 2020). "In this study, we first investigated the role of KLF5 in EMT and the migration of liver cancer cells." (PMID 32965165, 2020).
prostate tumors (9 papers, 2015 to 2024). "Mechanistically, the KLF5 acetylation–dependent barrier induced by PTEN deficiency constrained prostate tumor growth by attenuating FGF receptor 1 (FGFR1) signaling." (PMID 38781024, 2024). "These GSEA data clearly indicate that interruption of Klf5 acetylation at K358 further enhanced FGFR1 signaling in Pten-deficient prostate tumors." (PMID 38781024, 2024). "In our recent study genome profiling SA derived prostate tumours, we describe a molecular taxonomy we call global mutational subtypes (GMSs), identifying a single KLF5 African-specific predicted cancer driver mutation." (PMID 38052806, 2023). "During tumorigenesis, the deletion of Klf5 promotes Pten loss-induced prostate tumors, and the Klf5-/-/Pten-/- tumors also have increased basal to luminal differentiation." (PMID 32245249, 2020). "Our recent study demonstrated that Klf5 loss in Pten-null prostate tumors also activates PI3K/AKT signaling by upregulating multiple extracellular growth factors (e.g. EGF), cytokines and their receptors." (PMID 25896712, 2015). "PTEN deficiency induces KLF5 acetylation in mouse and human prostate tumors." (PMID 38781024, 2024). "Interruption of Klf5 acetylation by the K358R mutation promotes Pten-null prostate tumor growth." (PMID 38781024, 2024). "Collectively, interruption of Klf5 acetylation at K358 promoted prostatic tumor growth by accelerating cell proliferation." (PMID 38781024, 2024). "Klf5KR knockin gave rise to more and larger organoids, indicating a role of deAc-KLF5 in promoting prostate tumor growth." (PMID 38781024, 2024). "In summary, we found that deletion of Klf5 promoted angiogenesis in Pten deletion-initiated mouse prostate tumors." (PMID 25896712, 2015). "KLF5 loss enhances tumor angiogenesis by attenuating PI3K/AKT signaling and subsequent accumulation of HIF1α in PTEN deficient prostate tumors." (PMID 25896712, 2015). "First, we tested whether prostate tumors grown in the bone express more Ac-KLF5 than those grown subcutaneously." (PMID 33731701, 2021). "Deletion of KLF5 can result in a decrease in PI3K/AKT signaling and accumulate HIF1α in prostate tumors to promote tumor angiogenesis." (PMID 31341536, 2019). "Our recent study established that Klf5 deletion leads to the activation of PI3K/AKT and ERK signaling in mouse prostate tumors." (PMID 25896712, 2015).
Hypertension (8 papers, 2011 to 2025). The presence of chronic increased pressure in the systemic arterial system. "The current study demonstrated the associations of KLF4 and KLF5 genetic variants with hypertension, as well as the association of the indicative variations in mRNA expression levels of KLF4 and KLF5 with the risk of hypertension and antihypertensive treatment." (PMID 39187911, 2024). "In mice, KLF5 has been found to play a role in the development of aortic thickening induced by hypertension." (PMID 39187911, 2024). "Our findings demonstrate the associations of KLF4 and KLF5 genetic variants with hypertension risk, as well as the indicative roles of mRNA expression levels of KLF4 and KLF5 in hypertension and antihypertensive treatment." (PMID 39187911, 2024). "It was found to be highly expressed in the interstitial tissue of SHR and amplifies hypertension in SHR by activating KLF5 to secrete several enzymes and growth factors, such as ACE." (PMID 36653797, 2023). "In spontaneous hypertension, overexpression of complement 3 enhances the promoter activity of KLF5, inducing the switch to the synthetic phenotype of VSMCs." (PMID 33493334, 2021). "We found increased levels of KLF5 in human and rodent pulmonary hypertensive lung tissues compared to normotensive lung samples." (PMID 21951574, 2011).
non-small cell lung carcinoma (8 papers, 2015 to 2025). A group of at least three distinct histological types of lung cancer, including non-small cell squamous cell carcinoma, adenocarcinoma, and large cell carcinoma. "The targeting relationship between KLF5 and miR-214-5p has been established in non-small cell lung cancer." (PMID 38609873, 2024). "Knockdown of krüppel-like factor 5 (KLF5) was reported to inhibit hypoxia-induced cell survival and promote cell apoptosis in non-small cell lung cancer (NSCLC) cells via direct regulation of hypoxia inducible factor-1α (HIF-1α) expression." (PMID 29898734, 2018).
renal fibrosis (8 papers, 2020 to 2025). A final common manifestation of a wide variety of chronic kidney diseases characterized by glomerulosclerosis and tubulointerstitial fibrosis. "For example, TRAF6 mediates KLF5 K63-linked ubiquitination, promoting nuclear localization and enhancing gene activation, contributing to renal fibrosis regulation." (PMID 38735939, 2024). "In conclusion, our study elucidated the protective effect of the loss of KLF5 by inhibiting the transcription level of MX1 in LN‐induced renal fibrosis and injury." (PMID 37506140, 2023). "The in vivo and in vitro experiments indicated that the loss of KLF5 relieved renal fibrosis and injury in LN via downregulating the transcription level of MX1." (PMID 37506140, 2023). "In vivo and in vitro experiments showed the suppressive effect of HDAC6 suppression on renal fibrosis and inflammation can be abolished by KLF5 overexpression." (PMID 39412062, 2024). "Nevertheless, the KLF5 haploinsufficiency in bilateral ureteral obstruction mouse was found to ameliorate renal injury and dysfunction, despite its enhancement of renal fibrosis." (PMID 39412062, 2024). "In our previous study, KLF5 was found to act as a suppressor in renal fibrosis through regulating MX1." (PMID 39412062, 2024). "To further explore the biological function of KLF5 and MX1 in the progression of renal fibrosis, we transfected si‐KLF5 or cotransfected si‐KLF5 and oe‐MX1 into HK‐2 cells, followed by 24‐h stimulation with TGF‐β1." (PMID 37506140, 2023). "Injection of sh‐KLF5 or sh‐MX1 alone in MRL/lpr mice reduced renal fibrosis in LN, while simultaneous injection of sh‐KLF5 and ad‐MX1 exacerbated renal injury and fibrosis." (PMID 37506140, 2023). "A previous study reported that KLF5 was related to the regulation of renal fibrosis, tubulointerstitial inflammation, podocyte apoptosis, and renal cell proliferation." (PMID 37506140, 2023). "We found that LPA induced EMT and renal fibrosis in tubular epithelial cells by regulating KLF5 via the mitogen-activated protein kinase (MAPK)–serine-threonine kinase (AKT) pathway through LPAR1, thus contributing to the pathogenesis of DN." (PMID 36142408, 2022). "A previous report showed that KLF5 expression was increased in renal tubular cells in an in vivo model of unilateral ureteral obstruction and promoted renal fibrosis." (PMID 36142408, 2022). "In contrast, in Klf5+/– UUO‐mice, the expression of fn1 and tgfβ1 gene which encode for FN and TGF‐β were increased concurrent with increased renal fibrosis as compared to UUO‐WT mice." (PMID 33523554, 2021). "Recently, KLF5 was identified in the kidney and was shown to regulate podocyte apoptosis, renal cell proliferation, tubulointerstitial inflammation and renal fibrosis." (PMID 33523554, 2021). "Silencing KLF5 by siRNA reduced the expression of TGFβ and fibronectin induced in high‐dose MK‐treated HK‐2 cells and alleviated renal fibrosis." (PMID 33523554, 2021). "An important role for KLF5 in the kidney was recently reported, such that KLF5 regulated podocyte apoptosis, renal cell proliferation, tubulointerstitial inflammation and renal fibrosis." (PMID 33523554, 2021). "Moreover, KLF5 can regulate renal cell proliferation, podocyte apoptosis, renal fibrosis, renal tubulointerstitial inflammation, and other diseases." (PMID 40949127, 2025). "Considering the finding of our previous study that KLF5 promotes renal fibrosis in MRL/lpr mice, it is reasonable to speculate the possible effect of HDAC6/MAFF/KLF5 axis in LN." (PMID 39412062, 2024). "In this study, we explored the role of the HDAC6/MAFF/KLF5 axis in renal fibrosis and inflammation using both in vivo and in vitro experiments with the expectation to provide a theoretical basis for proposing new treatment approaches for LN patients, especially for pediatric patients." (PMID 39412062, 2024). "Knockdown of KLF5 mitigated renal fibrosis in LN by inhibiting MX1 transcription." (PMID 37506140, 2023).
renal fibrosis (continued). "Knockdown of KLF5 alleviated renal fibrosis in LN through repressing the transcription of MX1." (PMID 37506140, 2023). "KLF5 has been linked to the development of renal fibrosis through stimulation of the HIF-1α-KLF5-TGF-β1 pathway, and silencing of the protein has relieved renal fibrosis produced by high-dose MK-treated HK-2 cells by lowering TGF-β and fibronectin expression." (PMID 35457114, 2022). "Hence, KLF5 regulated renal fibrosis and injury in LN via MX1." (PMID 37506140, 2023). "Overall, HDAC6 aggravated renal fibrosis and inflammation in mice with LN via the MAFF/KLF5 signaling axis." (PMID 39412062, 2024). "This study aims to elucidate the role of Kruppel‐like factor (KLF5) and myxovirus resistance 1 (MX1) in the progression of renal fibrosis in lupus nephritis (LN)." (PMID 37506140, 2023). "Consistent with our previous results, the KLF5 expression in this study was found to be increasingly presented in renal tissues of MRL/lpr mouse and in renal epithelial cells, whose regulation on renal fibrosis and inflammation in LN was further confirmed by in vivo experiments." (PMID 39412062, 2024). "This study explored the possible effect and involvement of HDAC6 in regulating renal fibrosis and inflammation in LN using both in vivo and in vitro experiments and highlighted the promotive effect of HDAC6 on LN progression through regulating the MAFF/KLF5 axis." (PMID 39412062, 2024).